KDM4B (lysine demethylase 4B)
Diseases named in the same sentence as KDM4B in open-access papers (continued):
Sharing a sentence is not in itself a finding about the gene and the disease.
cancer (53 papers, 2011 to 2025). A tumor composed of atypical neoplastic, often pleomorphic cells that invade other tissues. "This strongly suggests that both H3.3G34R and IDH1R132H can inhibit KDM4B activity, and that inhibition of KDM4B is a common component in promoting ALT in ATRX-mutated cancers." (PMID 33972520, 2021). "Our results suggest that in ATRX-mutated ALT cancers, loss of KDM4B results in an increase of H3K9me3- and HP1α-containing heterochromatin to a level that can sustain and stabilise the formation of APBs." (PMID 33972520, 2021). "The clinical significance of KDM4B inactivation in other ATRX-mutated ALT cancers requires further studies." (PMID 33972520, 2021). "KDM4B, as a histone demethylase, functions as an oncogenic factor in many cancers and is implicated in osteoclastogenesis as well as pro-inflammatory cytokine release in inflammatory diseases." (PMID 33909202, 2021). "Conversely, KDM4B over-expression in ALT cancer cells abrogates ALT-associated features." (PMID 33972520, 2021). "KDM4B plays important roles in the self-renewal of embryonic stem cells and the conversion of induced pluripotent stem cells, and is linked to many forms of cancer." (PMID 29342868, 2018). "Importantly, these enzymes may also be targeted by other cancer-associated pathways (e.g., regulation of KDM4B by HIF and estrogen receptor in breast cancer cells) and this convergence emphasizes the importance of the induction of these enzymes in cancer." (PMID 33171917, 2020). "In both cancer cell lines, the reduction in KDM4B expression was similar in the cells co-transfected with targeting sgRNAs, with or without CRISPRoff." (PMID 40537846, 2025). "KDM4B is frequently overexpressed in various cancers, where it promotes gene expression under hypoxic conditions and enhances metabolic activity in castration-resistant prostate cancer (CRPC) by functioning as a coactivator of c-Myc." (PMID 40872531, 2025). "For instance, ER+ BCs exhibit overexpression of KDM4A and KDM4B; the two enzymes promote cancer growth and metastasis by targeting either the Notch1-NICD-dependent signaling (for KDM4A) or the estrogen signaling (for KDM4B) pathways." (PMID 40141248, 2025). "To investigate the impact of KDM4B on the type I IFN signature in human cancers, we evaluated the levels of IFN‐β and downstream proteins." (PMID 38390756, 2024). "Given such unexpected and remarkable potency of KDM4B inhibition observed in both clinical settings and our experimental systems, we proceeded to shift our focus towards investigating the clinical relevance of KDM4B in human cancers." (PMID 38390756, 2024). "In general, our results demonstrate that KDM4B is commonly upregulated in cancer cells and highly correlated with the poor type I IFN signature, immunosuppressive TME, worse prognosis and inadequate response to immunotherapy." (PMID 38390756, 2024). "In cancer, abnormal expression of KDM4B leads to excessive opening of chromatin and promotes oncogene transcription." (PMID 38093312, 2023). "Abnormal expression of KDM4B, a histone demethylase, is often considered an indicator of a poor prognosis in many cancers." (PMID 38093312, 2023). "Together, our findings suggest that KDM4B silencing suppresses cancer cell survival, proliferation, migration, and invasion through the MYC signaling pathway." (PMID 38093312, 2023). "These family members are involved in diverse biological pathways linked to cancer such as Akt-mTOR signaling for KDM4A, Wnt signaling for KDM4B, targeting pluripotency factors for KDM4C, and hypoxia-inducible factor 1 signaling for KDM4D." (PMID 36975603, 2023). "KDM4B has been found to function as an oncoprotein in a variety of cancers, but such reports in GBM are rare." (PMID 38093312, 2023). "This dual function of KDM4B in cancer progression indicates its potential for serving as a cancer therapeutic target." (PMID 34766154, 2021).
cancer (continued). "Overall, our findings suggest that KDM4B plays complex roles in regulating multiple cancer processes, providing a useful resource for the future development of cancer therapies that target KDM4B expression." (PMID 34766154, 2021). "We also provide a relatively complete report of the progress of research related to KDM4B inhibitors and discuss their potential as therapeutic agents for overcoming cancer." (PMID 35186950, 2021). "KDM4B is frequently overexpressed in many cancers and is involved in diverse biological processes such as DNA damage, cell death, and cell-cycle arrest." (PMID 33909202, 2021). "In this review, we discuss the diverse roles of KDM4B in contributing to cancer progression and normal developmental processes." (PMID 35186950, 2021). "Because of its ability to promote gene expression, KDM4B is utilized as an intermediate binding protein by many oncoproteins in various types of cancers." (PMID 35186950, 2021). "TCGA data analyses reveal high expression of KDM4B in multiple cancer types and differential expression across cancer stages." (PMID 34766154, 2021). "It will be interesting to investigate if FH and SDHx mutations also inhibit KDM4B and act as cooperating factors to promote ALT in ATRX-mutated cancers." (PMID 33972520, 2021). "Since we observed a common KDM4B regulatory mechanism among OVCAR, CRC, and RCC, we next sought to further evaluate the potential benefit of targeting the KDM4B pathway in different cancers." (PMID 34766154, 2021). "Radiation was a negative regulator of KDM4B expression and regulates global histone methylation of cancer cells." (PMID 35186950, 2021). "In recent years, inhibitors of KDM4B have been developed, providing more new ideas for targeted cancer therapy." (PMID 35186950, 2021). "More important, when expression data for both TCL and KDM4B in CRC patients were extracted from publicly available cancer database (TCGA), a strong positive correlation was identified." (PMID 34249900, 2021). "In these reported cancers, the expression of KDM4B in cancer tissues is indeed higher than that in normal tissues, which indicates abnormal expression." (PMID 35186950, 2021). "KDM4B has been shown to contribute to cancer development and progression by regulating the transcription of a myriad of cancer-related genes." (PMID 34249900, 2021). "We classified cancer cases into high KDM4B and low KDM4B expression groups and utilized the Kaplan–Meier plotter tool to investigate the correlation of KDM4B expression with the prognosis of patients with various cancers." (PMID 34766154, 2021). "Supporting this, ectopic expression of KDM4B in established ALT cancer lines leads to dissociation of APBs and increased DNA damage at telomeres." (PMID 33972520, 2021). "Knockdown of KDM4B decreases NB cell proliferation in vitro and NB xenograft growth in vivo, which provides proof-of-concept for the potential therapeutic efficacy of inhibiting KDM4B to target oncogenic MYCN signaling in cancers." (PMID 33628735, 2020). "KDM4B also plays an important role in cancer metastasis, DNA damage response and cell differentiation." (PMID 31931846, 2020). "Since GLUT1 is essential for cancer cell glucose uptake, we then examined the effect of KDM4B on GLUT1 expression." (PMID 31931846, 2020). "Two KDM enzymes, KDM3A and KDM4B, which remove transcriptionally repressive H3K9me1/me2 and H3K9me2/me3 marks, respectively, have both been associated with oncogenic roles in numerous cancer types, suggesting that perturbation of their activity may be efficacious as a therapeutic option." (PMID 31390833, 2019). "Experiments using human cancer cells and knockout mouse models demonstrated a role for KDM4B as an essential factor for estrogen-dependent gene expression and for growth and differentiation of the mammary epithelium." (PMID 30759871, 2019). "Hypoxia is also an independent oncogenic driver and both KDM3A and KDM4B are co-activators of HIF-1α signalling in multiple cancer types." (PMID 31390833, 2019).
cancer (continued). "The hypoxic induction of KDM4B in multiple cell types makes it a particularly compelling target for studying epigenetic regulatory mechanisms in various cancers." (PMID 30759871, 2019). "Further, we discussed the estrogen and hypoxia pathways converging at histone demethylase KDM4B, an important epigenetic modifier in cancer." (PMID 29342868, 2018). "KDM4B is amplified in medulloblastoma and malignant peripheral nerve sheath tumors, and is overexpressed in many other cancers." (PMID 29342868, 2018). "Recently, efforts have been made by us and other groups to identify and develop KDM4B inhibitors for cancer treatment." (PMID 29342868, 2018). "In normoxia, KDM4B predominantly regulated genes involved in cancer, cell cycle (including DNA replication, recombination and repair) and cell death pathways." (PMID 27869162, 2017). "Hypoxic regulation of KDM4B is a common mechanism in many different cancer cell types, suggesting that KDM4B would also be robustly expressed in EOC." (PMID 27869162, 2017). "Inhibition of KDM4B can also be used to treat other cancers." (PMID 40940894, 2025). "Moreover, KDM4B plays crucial roles in cancer progression and bone homeostasis by regulating osteoclast differentiation and bone remodeling, with its loss linked to skeletal aging and osteoporosis." (PMID 40872531, 2025). "Our analysis revealed a negative association between KDM4B expression and most immune cell infiltration, especially lymphocytes and dendritic cells in almost all cancers, underscoring KDM4B's role in fostering an immunosuppressive TME." (PMID 38390756, 2024). "Notably, in the TCGA pan‐cancer database, samples exhibiting low KDM4B expression displayed elevated levels of IFN‐β, CXCL10, ISG15, PD‐L1 and PD‐1, in contrast to those with high KDM4B expression." (PMID 38390756, 2024). "According to the genome-wide analysis, KDM4B might be a cancer-specific regulator of alternative splicing by regulating additional alternative splicing-related genes involved in tumorigenesis." (PMID 36755810, 2023). "Scientists suggest that KDM4B is an effective target and that blocking it could disrupt the interactions between cancer cell proteins." (PMID 35186950, 2021). "Taken together, these findings clearly show that KDM4B acts as an oncogene in these other cancers." (PMID 35186950, 2021). "In conclusion, regulation of histone demethylase KDM4B, which is a potential therapeutic target, might improve the efficacy of cancer treatment." (PMID 35186950, 2021). "KDM4B is a key epigenetic factor that plays important roles in multiple cancer types." (PMID 34766154, 2021). "Kaplan–Meier plots suggest that elevated KDM4B expression may contribute to a better or worse prognosis in a manner specific to each cancer type." (PMID 34766154, 2021). "To determine whether KDM4B regulates mechanisms that are commonly shared by multiple cancers or that are unique for each cancer type, we identified KDM4B‐dependent genes in SKOV3ip.1, HCT116, and RCC4 cell lines." (PMID 34766154, 2021). "As a direct target of hypoxia‐inducible factor, lysine demethylase 4B (KDM4B) is overexpressed in multiple cancers, suggesting that a general KDM4B regulatory mechanism may exist in these cancer types." (PMID 34766154, 2021). "Two of the 16 positively regulated genes, ERO1L and LOXL2, are involved in vascular endothelial growth factor (VEGF) secretion and extracellular matrix (ECM) remodeling, respectively, suggesting KDM4B is essential for the general malignant phenotypes that are shared by multiple cancers." (PMID 34766154, 2021). "KDM4B function has been studied in many cancer types (reviewed by Wilson et al15)." (PMID 34766154, 2021). "In this study, we sought to determine the role KDM4B plays in these three cancer types, whether it regulates general or unique gene expression signatures and if there is a correlation between KDM4B regulatory mechanism and the hypoxia‐induced HIF signaling." (PMID 34766154, 2021).
cancer (continued). "By using microarray analysis, we have identified 26 KDM4B‐dependent genes (16 genes were positively regulated by KDM4B, and 10 genes were negatively regulated by KDM4B) commonly shared by SKOV3ip.1, HCT116, and RCC4 cells, indicating a general regulation of KDM4B in different cancer types." (PMID 34766154, 2021). "KDM4B is highly expressed in multiple cancers and is differentially expressed across cancer stages." (PMID 34766154, 2021). "A majority of these KDM4B‐dependent downstream targets are involved in cancer‐related pathways." (PMID 34766154, 2021). "Therefore, KDM4B as a cancer target must be supported by more animal and clinical data, and new cancer treatments need to be developed and used." (PMID 35186950, 2021). "In this study, we have identified general, tissue‐specific, and oxygen‐specific KDM4B regulatory networks that may affect cancer progression." (PMID 34766154, 2021). "Consider the oncogenic role of KDM4B in multiple cancers, we wonder whether KDM4B can participate in glucose metabolism and the mechanism should be further investigated." (PMID 31931846, 2020). "In addition to developmental processes, KDM4B has been shown to play a significant role in cancer progression." (PMID 30759871, 2019). "In this review, we discuss what is known about the regulation of KDM4B in response to the cellular environment, and how this context-dependent expression may be translated into specific biological consequences in cancer and reproductive biology." (PMID 30759871, 2019). "Additionally, KDM4B is important for repair of DNA double strand breaks, and knockdown of KDM4B inhibits proliferation of cancer cells after induction of DNA damage." (PMID 30634491, 2019). "Collectively, we demonstrate that KDM4B may play an important role in mitochondrial apoptosis and represent a potential therapeutic cancer target in CRC." (PMID 27506941, 2016). "Furthermore, enhanced KDM4 activity or increased levels of KDM4B and/or KDM4C caused by intermittent hypoxia may also impact tumors, as the KDM4 group is associated with various cancers." (PMID 36174675, 2022). "Furthermore, we focus on recent studies highlighting the oncogenic functions of KDM4B in various kinds of cancers, which may be a novel therapeutic target for cancer treatment." (PMID 35186950, 2021). "Furthermore, KDM4B was revealed to be targeted by different microRNAs (miRNAs) in various cancers." (PMID 33732698, 2021). "Therefore, KDM4B is often considered as an oncogene in cancers." (PMID 35186950, 2021). "Therefore, studying the differentially regulated KDM4B targets in each cancer type and each patient may facilitate the design of precision therapies." (PMID 34766154, 2021). "However, in cancer, the carcinogenic mechanism of KDM4B is due to an abnormal increase in its expression, resulting in activation of multiple oncogene signaling pathways by histone demethylation, such as binding with MYC, AR or ER to promote the expression of downstream genes." (PMID 35186950, 2021). "Thus, further studying KDM4B regulatory mechanism in various cancer types may help discover targeted therapy that can benefit a broader spectrum of cancer patients." (PMID 34766154, 2021). "We suggest that KDM4B may represent a potential therapeutic cancer target in CRC." (PMID 27506941, 2016). "In pancreatic cancer, KDM4B regulates the expression of ZEB1 during TGF-β–induced epithelial-to-mesenchymal transition (EMT), and its silencing significantly impairs cancer cell migration, invasion, and EMT." (PMID 40872531, 2025). "KDM4B, a member of the lysine demethylase 4 (KDM4/JMJD2) family, has emerged as a crucial regulator in various pathological conditions, including cancer, aging, and obesity." (PMID 40595456, 2025).
cancer (continued). "KDM4B disrupts the DNA damage repair (DDR) machinery, leading to cellular transformation and immortalization, a key step in cancer development." (PMID 39764127, 2024). "Accumulating evidence supports the oncogenic potential of KDM4A, KDM4B, and KDM4C, which are overexpressed in several types of cancer, including PCa." (PMID 35534851, 2022). "KDM4B is a member of the KDM4/JMJD2 family that target H3K9me2/3 and H3K36me3 and are frequently overexpressed in human cancer cells and neoplastic tissues." (PMID 33588776, 2021). "KDM4B regulates the expression of key oncogenes, such as C-MYC and CDK6, and is involved in cancer invasiveness, metastasis, and therapeutic resistance." (PMID 29342868, 2018). "Given that these KDM4 demethylases, especially KDM4B and KDM4C, are involved in an array of cancers, targeting the catalytic activity of these demethylases could have therapeutic potential." (PMID 36975603, 2023). "Accumulating evidence suggests the cancer drivers KDM4A, KDM4B, and KDM4C are overexpressed leading to the efficient growth, in a variety of human malignancies including breast, colorectal, lung, prostate, and other cancers." (PMID 36520265, 2022). "We next sought to evaluate whether KDM4B is the key member of the KDM4 family (KDM4A, KDM4B, and KDM4C) for controlling c-Myc to regulate cancer metabolism." (PMID 34335964, 2021). "In cancer research, the KDM4B protein itself has not been reported to induce carcinogenesis through the generation of mutations." (PMID 35186950, 2021). "Coupled with the finding that KDM4B also regulates KDM3A expression and that KDM3A regulates both KDM4B and FOXA1 deposition at ER cis-regulatory sites, our data suggests a potential co-regulatory relationship between all three proteins to facilitate a cancer phenotype in ER-positive BC." (PMID 31390833, 2019). "Considering the proposed co-regulatory relationship between KDM3A, KDM4B, and FOXA1, which facilitates a cancer phenotype in ER-positive BC, these data together suggest that targeting KDM3A and KDM4B simultaneously may be an efficacious therapeutic strategy." (PMID 31390833, 2019). "Although a systematic comparison has not been conducted, KDM4B appears to regulate pathways distinct to each cancer type studied." (PMID 27869162, 2017). "KDM4B phosphorylation by RSK is critical for KDM4B retention in chromatin for the repair of DNA double-strand breaks, which may provide a new role for RSK inhibitors in cancer therapy." (PMID 39434131, 2024). "Besides LSD1, enzymes involved in histone lysine methyltransferases and lysine demethylases, such as SUV39H1 (KMT1A), SETDB1 (KMT1E), KDM4B, and KDM5A, have been found to be involved in the DDR, suggesting that their inhibitors have combination therapy potential with PARPi for cancer treatment." (PMID 37973845, 2023). "The majority of KDM4B targets were specific for each cell line (774 positive/588 negative for SKOV3ip.1, 207 positive/275 negative for HCT116, and 934 positive/839 negative for RCC4), suggesting that KDM4B also regulate unique gene expression signatures in each cancer type." (PMID 34766154, 2021). "In the case of the KDM4 family, where elevated expression seems to be a hallmark of many cancers, it may not be important to distinguish between KDM4A, KDM4B, KDM4C, and KDM4D." (PMID 30759871, 2019). "Altogether, these observations show for the first time that depletion of KDM4C, but not KDM4B, affects the fidelity of mitotic chromosome segregation, therefore suggesting that CIN in cancers lacking KDM4C can result in part from mitotic chromosome missegregation." (PMID 24728997, 2014).